TMIE (transmembrane inner ear)
Description:
Auxiliary subunit of the mechanotransducer (MET) non-specific cation channel complex located at the tips of stereocilia of cochlear hair cells and that mediates sensory transduction in the auditory system. The MET complex is composed of two dimeric pore-forming ion-conducting transmembrane TMC (TMC1 or TMC2) subunits, and aided by several auxiliary proteins including LHFPL5, TMIE, CIB2/3 and TOMT, and the tip-link PCDH15. May contribute to the formation of the pore.
Synonyms: DFNB6
Tractability: Antibody: UniProt predicts a signal peptide or a membrane-spanning region.
Gene: Protein-coding gene on chromosome 3 (46,694,528 to 46,710,886, forward strand). Ensembl gene ENSG00000181585.
Subcellular location: Membrane
Subcellular location (Human Protein Atlas): Cytosol; Vesicles
Pathways (Reactome):
Sensory Perception: Sensory processing of sound by inner hair cells of the cochlea; Sensory processing of sound by outer hair cells of the cochlea
Gene Ontology:
Biological process: inner ear morphogenesis; sensory perception of sound
Cellular component: membrane
Genetic constraint (gnomAD): Loss-of-function variants: 14 observed, 14.8 expected, observed/expected ratio (o/e) 0.95, 90% interval 0.62 to 1.48. The upper end of that interval is the gene's LOEUF score, 1.48, which puts it in group 6 of 6, group 1 being the genes least tolerant of losing a copy. Missense variants: 204 observed, 198.61 expected, observed/expected ratio (o/e) 1.03, 90% interval 0.92 to 1.15. Synonymous variants: 75 observed, 81.15 expected, observed/expected ratio (o/e) 0.92, 90% interval 0.77 to 1.12.
Gene-disease validity (ClinGen):
ClinGen rates the evidence that TMIE causes each of these diseases.
nonsyndromic genetic hearing loss (autosomal recessive): Definitive. A disease characterized by hearing loss that is not part of a larger syndrome.
Homologues: Orthologues: chimpanzee TMIE (98% identical), dog TMIE (92% identical), mouse Tmie (92% identical), rat Tmie (92% identical), pig TMIE (90% identical), guinea pig TMIE (89% identical), rabbit TMIE (74% identical).
Diseases named in the same sentence as TMIE in open-access papers:
TMIE is named in the same sentence as 6 diseases in open-access papers, as found by Europe PMC text mining. Sharing a sentence is not in itself a finding about the gene and the disease. The quoted sentences say what the papers report.
deafness (9 papers, 2014 to 2022). An inherited or acquired condition characterized by the complete loss of the ability to hear from one or both ears. "Loss-of-function mutations in the evolutionarily conserved protein TMIE were causally associated with autosomal recessive deafness-6 (DFNB6; OMIM: 600,971) in human and animal studies." (PMID 35710363, 2022). "Multiple point mutations in TMIE are linked to deafness, and recent studies suggest a role for TMIE in TMC-1 and TMC-2 localization and channel gating." (PMID 36224384, 2022). "Autosomal recessive deafness-6 (DFNB6) is caused by mutated TMIE, a gene in the high genetic heterogeneity spectrum of deafness." (PMID 35710363, 2022). "Previous reports on TMIE demonstrated that loss of TMIE function resulted in deafness in fish, mice and humans, indicating the importance and conserved function of this gene among vertebrates." (PMID 34093131, 2021). "The del(GJB6-D13S1830), SERPINB6, TMIE, COCH, ESPN, ACTG1, GJB3, and KCNQ4 mutations were infrequently associated with deafness in the Moravian-Silesian population." (PMID 30344259, 2018). "TMIE was first identified as a deafness gene in mice and humans." (PMID 30726219, 2019).
hearing loss (5 papers, 2014 to 2024). "Mutations in the autosomal genes TMPRSS3, TMC1, USHIC, CDH23 and TMIE are known to cause hereditary hearing loss." (PMID 24416283, 2014). "Duman et al32 determined a frequency of 6.6% for all recognized mutations of the TMIE gene in 49 Turkish families with non‐syndromic hearing loss, whereas among 374 Indian families affected by autosomal recessive non‐syndromic hearing loss, the frequency of the TMIE gene was about 1.6%." (PMID 33987950, 2021). "The MET channel consists of different subunits whose genes are involved in hearing impairment, namely they are transmembrane inner ear protein (TMIE), transmembrane channel like protein (TMC1), and tetraspan membrane protein of hair cell stereocilia (TMHS)." (PMID 33193648, 2020). "Furthermore, our study could help direct the clinical diagnosis of hearing loss related to aberrant splicing of TMC1, LHFPL5, and TMIE." (PMID 33509951, 2021).
auditory neuropathy (1 paper, 2023). A hearing disorder characterized by impaired transmission of signals through the auditory nerve, resulting in mild to severe hearing loss and poor speech perception. "Mutations in COL7A1 were reported to potentially overlap with the TMIE gene that is involved in the mechanoelectrical transduction of cochlear hair cells and detected in a case of bilateral auditory neuropathy." (PMID 37273692, 2023).
lipoma (1 paper, 2025). A benign, usually painless, well-circumscribed lipomatous tumor composed of adipose tissue. "Some components of the MET channel have been improved, such as transmembrane channel-like 1/2 (TMC1/2), transmembrane inner ear protein (TMIE), and lipoma HMGIC fusion partner-like 5 (LHFPL5)." (PMID 40076845, 2025).
TMIE also shares sentences with these, for which no sentence is quoted: Hearing impairment (2 papers); Autosomal recessive deafness-6 (1).